MIR543 (microRNA 543)
Synonyms: hsa-mir-543; MIRN543; mir-543
Gene: MicroRNA gene on chromosome 14 (101,031,987 to 101,032,064, forward strand). Ensembl gene ENSG00000212040.
Gene Ontology:
Biological process: miRNA-mediated post-transcriptional gene silencing
Cellular component: RISC complex